GRM5 (glutamate metabotropic receptor 5)
Diseases named in the same sentence as GRM5 in open-access papers (continued):
Sharing a sentence is not in itself a finding about the gene and the disease.
prion disease (5 papers, 2017 to 2026). A transmissible disease that is caused by a protein that is able to induce abnormal folding of normal cellular proteins, leading to characteristic spongiform brain changes, which are associated with neuronal loss without an inflammatory response. "For instance, the metabotropic glutamate receptors Grm5 and Grm8 mediate prion toxicity, while Bmerb147, Macrod246, and Stmn248 are implicated as putative genetic risk loci for prion disease." (PMID 39580485, 2024). "Although both Grm5 genetic deletion and mGluR5 pharmacological inhibition (MPEP) did not prevent prion disease, MPEP significantly improved locomotor abilities until the later stage of disease, decreased the size of spongiform vacuoles, and reduced the extent of hippocampal astrogliosis." (PMID 29176838, 2017).
lymphoma (4 papers, 2023 to 2024). A malignant (clonal) proliferation of B- lymphocytes or T- lymphocytes which involves the lymph nodes, bone marrow and/or extranodal sites. "Given our group’s previous findings of heterogeneous GRM5 expression in in vitro HL cell lines, the DAB staining results confirming the presence of mGluR5 in lymphoma tissues and the missing expression in healthy controls, we decided to further investigate the mGluR5 staining in HRS-cells." (PMID 39001514, 2024).
ischemic stroke (3 papers, 2015 to 2024). A stroke disorder caused by obstruction of blood flow to the brain, due to thrombotic (local blood clot formation) or embolic (due to a blood clot or other material traveling from another site) event. "Functional categorization analysis showed that BHD treatment preserved the integrity of the blood–brain barrier (BBB) (Alb, Fga, and Trf), suppressed excitotoxicity (Grm5, Gnai, and Gdi), and enhanced energy metabolism (Bdh), thereby revealing its multiple effects on ischemic stroke mice." (PMID 26492191, 2015).
myopia (3 papers, 2019 to 2025). "We also found that GRM5 was implicated in human myopia in the UK Biobank sample." (PMID 31362747, 2019). "Interestingly, the expression of the GRM5 gene, which was found to be highly enriched in the dopaminergic amacrine cells of the retina, correlated with susceptibility to myopia in mice." (PMID 31362747, 2019). "GSAP and GRM5/TYR genes are associated risk factors for the development of PDS, PG, and myopia." (PMID 36979429, 2023).
scrapie (3 papers, 2017 to 2022). A fatal disease of the nervous system in sheep and goats, characterized by pruritus, debility, and locomotor incoordination. "Surprisingly, a previous report and this study show that Grm5 ablation does not ameliorate the clinical manifestation of scrapie in vivo." (PMID 29176838, 2017).
type 1 diabetes (2 papers, 2011 to 2019). "Variants in the metabotropic glutamate receptor group I pathway, including GRM1 and GRM5, were enriched in the pathway analysis of a recent albuminuria GWAS among people with type 1 diabetes from the FinnDiane study (no individuals overlapped with the current gene-aggregate meta-analysis)." (PMID 30547231, 2019).
albinism (1 paper, 2013). A congenital disorder characterized by partial or complete absence of melanin pigment in the eyes, hair, or skin. "However, GRM5 and APBA2 lie 396 kb upstream and 1025 kb upstream of TYR and OCA2, respectively, two well-known pigmentary genes for which a complete loss-of-function causes albinism in humans and in other animals." (PMID 23555287, 2013).
autosomal recessive intellectual disability (1 paper, 2022). "It contains three genes GRM5, GRIK2, and GRIA4, and GluR6 is encoded by GRIK2 which is highly expressed in the brain and is associated with autosomal recessive intellectual disability." (PMID 36699455, 2022).
hearing loss (1 paper, 2021). "Associations linked to SYNJ2 and GRM5 point towards the cochlear conductance of auditory signals to play a role in hearing loss risk." (PMID 34847940, 2021).
hyperglycaemia (1 paper, 2020). "FDM-risk variants within these selective sweeps identified GRM5 and DLG2 as candidates for beta cell dysregulation, as both are involved in glucose-stimulated insulin secretion and hyperglycaemia susceptibility in rodent and human." (PMID 33154479, 2020).
squamous cell carcinoma (1 paper, 2019). A carcinoma arising from squamous epithelial cells. "The expression of GRM5 was up-regulated in squamous cell carcinoma and overexpression of GRM5 accelerated tumor growth." (PMID 31492116, 2019).
thyroid cancer (1 paper, 2022). "Several hypermethylated genes (GALNTL6, HTR7, SPOCD1, CDH16 and GRM5) related to thyroid cancer have been discovered to be up-regulated in our study, as were investigated in other reports to mentioned in the following text." (PMID 35267472, 2022).
Williams syndrome (1 paper, 2019). "The paradoxical increased social preference within an overall anxiogenic phenotype, as in the germ line Grm5-/- mice, shows remarkable analogies with Williams syndrome." (PMID 30873001, 2019).
neurological disorders (36 papers, 2012 to 2025). "Among the top 50 database-predicted targeted genes, 8 genes (HOMER1, FRAT2, GRM5, TGFBR1, KDM3A, RGS2, ARRB1, and YWHAZ) were reported to be associated with axonal/neuronal regeneration/or neurological diseases." (PMID 36959678, 2023). "So, by combining specific GO term–annotated gene lists and cross-checking with publications, we were able to decrease the number of candidate genes and predict candidate genes (FOXO4, GRM5, RIMS1 and NELL2) for neurological diseases." (PMID 23794737, 2013). "In LHQW, arctiin, corymbosin, and aloe-emodin target neurological disease-related genes (GRM1 and GRM5), whereas in QFPD, isofucosterol, baicalein, nobiletin, oroxylin A, epiberberine, and piperlonguminine target immunity- and inflammation-related genes (mTOR and PLA2G4A)." (PMID 36210820, 2022).
psychiatric disorder (28 papers, 2010 to 2025). A disorder characterized by behavioral and/or psychological abnormalities, often accompanied by physical symptoms. "PRKCE interacts with several proteins encoded by genes of potential relevance to psychiatric disorders, including the glutamate decarboxylases (GAD1, GAD2), NMDA receptors (GRIN2D, GRIN1), and a metabotropic glutamate receptor (GRM5)." (PMID 23922650, 2013).
tumor (26 papers, 2016 to 2026). "They had implicated ERK as a downstream effector of GRM5 signalling in tumours." (PMID 26730743, 2016). "The expression of mGluR1 (GRM1) and mGluR5 (GRM5) was conserved from primary tumours to metastatic samples, but moderate changes were evident for other receptors such as mGluR2/3/7/8 (GRM2, GRM3, GRM7, and GRM8)." (PMID 37173906, 2023). "Additional analysis has provided evidence that rs7102764 T was correlated with a higher expression of GRM5, which is consistently found to be upregulated in tumours, compared to normal tissues." (PMID 30488581, 2018). "A tendency of GRM5 gene upregulation was observed in tumour tissues, suggesting that this gene may play a role in RCC carcinogenesis." (PMID 30488581, 2018). "We did not detect any mGluR5 staining in tumor-free lymph nodes, which is consistent with the absence of GRM5 transcripts in RNA-sequencing data from non-malignant B and T cells." (PMID 39001514, 2024). "We did not see mGluR5 in tumor-free or reactive lymph nodes and found no relevant expression of GRM5 in RNA-sequencing data sets from isolated B and T lymphocyte populations." (PMID 39001514, 2024).
neurodegenerative disease (23 papers, 2013 to 2025). A disorder of the central nervous system characterized by gradual and progressive loss of neural tissue and neurologic function. "The other five genes, bound by Tau under HS conditions (as also Grm5), were chosen according to their implication in neurodegenerative diseases (Trex1, Dlg2, Dlg1, Xrcc6, Eif2a)." (PMID 30321409, 2018).
cancer (16 papers, 2013 to 2024). A tumor composed of atypical neoplastic, often pleomorphic cells that invade other tissues. "As mentioned in the results section, PLD network involves proteins such as LPAR4, LPAR6, HCRTR1, and GRM5, as well as pathways like EGF/EGFR SP, which their roles have been proven in initiation and progression of several cancers." (PMID 29062084, 2017).
GRM5 also shares sentences with these, for which no sentence is quoted: cognitive deficits (59 papers); autism (52); Parkinson disease (32); autoimmune encephalitis (22); Hodgkins lymphoma (19); Dyskinesia (16); mood disorder (11); neurodevelopmental disorder (11); amyotrophic lateral sclerosis (10); cognitive decline (10); memory impairment (10); migraine (10); tuberous sclerosis (10); alcohol use disorder (9); ischemia (8); brain disorder (7); cocaine addiction (7); dementia (7); gastroesophageal reflux disease (7); amyloid (6); anxiety disorder (6); multiple sclerosis (6); neuropathic pain (6); small cell lung carcinoma (6); insomnia (5); osteosarcoma (5); psychosis (5); Seizure (5); temporal lobe epilepsy (5); injury (4).
A further 136 diseases each share a sentence with GRM5 in 4 papers or fewer.